LINC01276 (long independently transcribed non-coding RNA 1276)
Gene: Long non-coding RNA gene on chromosome 6 (41,499,033 to 41,519,852, forward strand). Ensembl gene ENSG00000226917.
Diseases named in the same sentence as LINC01276 in open-access papers:
LINC01276 is named in the same sentence as 1 disease in open-access papers, as found by Europe PMC text mining. Sharing a sentence is not in itself a finding about the gene and the disease. The quoted sentences say what the papers report.
dilatation (1 paper, 2021). "Increased expression of LINC01276, a non-coding RNA gene, which has not been previously reported with increased LV dilatation, was also observed." (PMID 33810615, 2021).